MIR7853 (microRNA 7853)
Synonyms: hsa-mir-7853
Gene: MicroRNA gene on chromosome 6 (6,169,304 to 6,169,435, reverse strand). Ensembl gene ENSG00000263572.
Homologues: Orthologues: chimpanzee MIR7853 (100% identical).